STX16 (syntaxin 16)
Description:
SNARE involved in vesicular transport from the late endosomes to the trans-Golgi network.
Synonyms: Syn16; hsyn16; SYN-16
Tractability: Antibody: UniProt predicts a signal peptide or a membrane-spanning region. PROTAC: ubiquitination databases record sites on it; its protein half-life has been measured.
Gene: Protein-coding gene on chromosome 20 (58,651,261 to 58,679,526, forward strand). Ensembl gene ENSG00000124222.
Subcellular location: Golgi apparatus membrane; Cytoplasm (Isoform C)
Subcellular location (Human Protein Atlas): Vesicles
Pathways (Reactome):
Vesicle-mediated transport: Intra-Golgi traffic; Retrograde transport at the Trans-Golgi-Network
Gene Ontology:
Molecular function: protein binding; SNAP receptor activity; syntaxin binding; SNARE binding
Biological process: endocytic recycling; retrograde transport, endosome to Golgi; intracellular protein transport; membrane fusion; vesicle-mediated transport
Cellular component: cytoplasm; focal adhesion; Golgi apparatus; Golgi cisterna; intracellular membrane-bounded organelle; perinuclear region of cytoplasm; SNARE complex; trans-Golgi network; Golgi membrane; trans-Golgi network membrane; cytosol; membrane; synaptic vesicle membrane
Genetic constraint (gnomAD): Loss-of-function variants: 26 observed, 36.92 expected, observed/expected ratio (o/e) 0.7, 90% interval 0.51 to 0.98. The upper end of that interval is the gene's LOEUF score, 0.98, which puts it in group 4 of 6, group 1 being the genes least tolerant of losing a copy. Missense variants: 334 observed, 404.7 expected, observed/expected ratio (o/e) 0.83, 90% interval 0.75 to 0.9. Synonymous variants: 144 observed, 151.07 expected, observed/expected ratio (o/e) 0.95, 90% interval 0.83 to 1.1.
Homologues: Orthologues: chimpanzee STX16 (99% identical), macaque STX16 (98% identical), guinea pig STX16 (95% identical), mouse Stx16 (94% identical), rat Stx16 (94% identical), pig STX16 (93% identical), dog STX16 (90% identical), rabbit STX16 (83% identical), tropical clawed frog stx16 (83% identical), zebrafish stx16 (77% identical), Drosophila melanogaster Syx16 (40% identical), Caenorhabditis elegans syx-16 (33% identical). Paralogues in human: STX4 (22% identical), STX12 (21% identical), STX1B (21% identical), STX1A (20% identical), STX2 (20% identical), STX7 (20% identical), STX3 (18% identical), STX5 (18% identical), TSNARE1 (18% identical), STX11 (18% identical), STX19 (14% identical), STX17 (10% identical).
Diseases named in the same sentence as STX16 in open-access papers:
STX16 is named in the same sentence as 25 diseases in open-access papers, as found by Europe PMC text mining. Sharing a sentence is not in itself a finding about the gene and the disease. The quoted sentences say what the papers report.
pseudohypoparathyroidism (4 papers, 2020 to 2025). "Current research on STX16 primarily focuses on its role in pseudohypoparathyroidism (PHP), particularly PHP1b, in which STX16 deletions are implicated in abnormal methylation of the GNAS locus, leading to endocrine resistance." (PMID 41266441, 2025). "Pseudohypoparathyroidism was confirmed by molecular identification of the 3-kb STX16 deletion." (PMID 33320452, 2020). "Despite the thorough analysis, no known pathogenic variants were found in genes typically associated with Fahr’s syndrome (e.g., XRP1, PDGFRB, JAM2, PDGFB, SLC20A2, or MYORG) or pseudohypoparathyroidism (e.g., GNAS, STX16, or GNASAS1)." (PMID 39519162, 2024).
breast carcinoma (2 papers, 2017 to 2021). "However, it appears to be a direct target gene of miR-19a, an oncogenic miRNA in breast cancer, and the STX16-NPEPL1 fusion event occurs in gastrointestinal stromal tumors." (PMID 33671634, 2021). "Finally, only 1 (BCAS4/BCAS3), 1 (BSG/NFIX), 2 (STX16/RAE1, RAB22A/MYO9B) and 0 fusions have been reported by all the tools within the considered breast cancer cell lines." (PMID 28114882, 2017).
pseudohypoparathyroidism type 1B (2 papers, 2022 to 2024). Pseudohypoparathyroidism type 1B (PHP-1b) is a type of pseudohypoparathyroidism (PHP) characterized by localized resistance to parathyroid hormone (PTH) mainly in the renal tissues which manifests with hypocalcemia, hyperphosphatemia and elevated PTH levels. "A2 methylation of GNAS is regulated by STX16 and NESP55 imprinting control regions, and GNAS A2 methylation status enables pseudohypoparathyroidism type 1B categorization." (PMID 38290008, 2024).
cyst (1 paper, 2013). A sac-like closed membranous structure that may be empty or contain fluid or amorphous material. "Our findings reveal that Stx16 depletion causes E-cadherin degradation in lysosomes, altered spindle orientation during the proliferation involved in cystogenesis in Matrigel, and the formation of multiple lumens within the cyst." (PMID 23626741, 2013). "Although lack of Stx16 results in the formation of multiple lumens, apical polarity with respect to the individual lumen in a cyst was maintained, suggesting that Stx16 does not alter the trafficking of apical markers in polarized cells." (PMID 23626741, 2013).
glaucoma (1 paper, 2020). Increased pressure in the eyeball due to obstruction of the outflow of aqueous humor. "Moreover, we identified Rab5b, App, Stx16, Pikfyve, Dnaja3, Cltc and Dlg4 as key genes impacting glaucoma pathogenesis by transcription differences." (PMID 33133146, 2020).
Hypokalemia (1 paper, 2022). An abnormally decreased potassium concentration in the blood. "No other mutations in GNAS or hypokalemia related genes and no deletions of STX16 exons were detected." (PMID 35410271, 2022).
macrosomia (1 paper, 2021). "STX16 (syntaxin 16) encoded a protein that is a member of the syntaxin or t-SNARE family, and deletion of this gene caused obesity and macrosomia in humans." (PMID 34107880, 2021).
Obesity (1 paper, 2021). Accumulation of substantial excess body fat. "For instance, a significant positive association between log (root−to−tip ω) and log (body mass) was tested in BRAP, STX16, ZGRF1 and ZPLD1, and all four genes were reported to cause obesity in humans." (PMID 34107880, 2021).
pulmonary fibrosis (1 paper, 2022). Chronic progressive interstitial lung disorder characterized by the replacement of the lung tissue by connective tissue, leading to progressive dyspnea, respiratory failure, or right heart failure. "Furthermore, the downstream protein-coding gene, STX16, is shown to interact with the N-terminal region of CFTR (cystic fibrosis transmembrane conductance regulator) in epithelial cells, suggesting a possible relation to pulmonary fibrosis." (PMID 35202087, 2022).
cancer (4 papers, 2013 to 2025). A tumor composed of atypical neoplastic, often pleomorphic cells that invade other tissues. "Statistically significant associations, corrected for multiple testing, were observed for the transcripts TBX21 and TGFBR3, which are mediators of the immune system, and LGR6 and STX16 that have been repeatedly associated with cancer progression." (PMID 24194869, 2013). "In some cancer types, STX16 expression levels have been correlated with patient prognosis, but its specific role in ccRCC has not yet been thoroughly investigated." (PMID 41266441, 2025). "STX16 has been studied in various cancers, where it is suggested to regulate tumor cell proliferation, migration, and invasion by affecting vesicle trafficking and signal transduction pathways." (PMID 41266441, 2025). "Given STX16’s central role in regulating lysosomal function, autophagy, and immune surveillance, targeting STX16 represents a promising therapeutic strategy in cancer treatment." (PMID 41266441, 2025). "NPEPL1 is a probable aminopeptidase and it has been found to form a fusion with STX16 in cancer tissue." (PMID 33827643, 2021). "Cancer cells exploit autophagy to withstand metabolic and therapeutic challenges, and STX16-mediated lysosomal fusion may be pivotal in this adaptation." (PMID 41266441, 2025). "A disruption in STX16-mediated membrane fusion may impair lysosomal degradation, leading to the accumulation of cellular waste and promoting the progression of cancer by increasing cellular stress and inducing inflammatory responses." (PMID 41266441, 2025). "As a member of the SNARE protein family, STX16 is involved in processes such as membrane fusion and intercellular communication, which are critical for cellular proliferation and migration and play a crucial role in cancer progression." (PMID 41266441, 2025). "Some of the prominent genes we identified through the networks are DOK5, APP, CTNND1, STX6, STX10, STX16, BACE1, and BACE2; which, agree with the regulation of various cancers based on their co-expression patterns in GeneMANIA." (PMID 37218885, 2023).
tumor (2 papers, 2025 to 2026). "Clinically, these findings highlight the potential of STX16 as a diagnostic and prognostic biomarker, warranting further investigation into its role in tumor initiation and development." (PMID 41266441, 2025). "Furthermore, the association of high STX16 expression with poorer survival across distinct pathological stages emphasizes its potential role in driving tumor progression." (PMID 41266441, 2025). "The positive association suggests that STX16 may modulate the recruitment and activation of these immune cells to promote an immune response against the tumor." (PMID 41266441, 2025). "Elevated STX16 expression was consistently associated with poor prognosis, regardless of immune cell infiltration levels, highlighting its potential role as a driver of tumor progression and a therapeutic target." (PMID 41266441, 2025). "Combining STX16-targeted therapies with existing immunotherapeutic approaches could synergistically enhance anti-tumor immune responses by reducing immune evasion associated with STX16 expression and improving the overall immune landscape within the tumor microenvironment." (PMID 41266441, 2025). "Beyond its role in vesicle fusion, STX16 appears to intersect with autophagy and lysosomal degradation—pathways essential for tumor cell survival under stress." (PMID 41266441, 2025). "Single-cell sequencing revealed heterogeneous STX16 expression across tumor microenvironment cell types." (PMID 41266441, 2025). "Such a role positions STX16 not only as a tumor-intrinsic factor but also as a regulator of tumor–immune interactions, potentially affecting the efficacy of immunotherapies." (PMID 41266441, 2025). "Its role in promoting tumor progression and modulating immune infiltration highlights STX16 as a potential biomarker and therapeutic target in ccRCC." (PMID 41266441, 2025). "Reduced cell viability and impaired invasive capabilities further highlight STX16’s role in promoting tumor aggressiveness." (PMID 41266441, 2025). "Single-cell transcriptomic analysis provided a high-resolution map of STX16 expression across diverse cell types in ccRCC and adjacent tissues, highlighting its enrichment not only in tumor epithelial cells but also in immune and stromal compartments." (PMID 41266441, 2025). "Western blot and IHC analyses confirmed that STX16 was overexpressed in ccRCC tumor tissues relative to normal tissues, consistent with bioinformatics results." (PMID 41266441, 2025). "Clinically, higher STX16 expression correlated with advanced tumor stage and higher T and N classification, supporting its role in tumor growth and lymph node metastasis." (PMID 41266441, 2025). "High STX16 expression correlated with advanced tumor stages, poor overall survival (OS), and disease-specific survival (DSS)." (PMID 41266441, 2025). "Given STX16’s potential involvement in intracellular transport and signaling pathways, it may play a crucial role in tumor progression." (PMID 41266441, 2025). "Disruption of STX16 may, therefore, alter immune cell behavior, impairing the tumor’s ability to mount an effective immune response." (PMID 41266441, 2025). "Our results demonstrated a significant positive correlation between STX16 expression and the infiltration of immune cells, suggesting that STX16 may play an important role in enhancing adaptive immune responses in the tumor microenvironment." (PMID 41266441, 2025). "Mechanistically, STX16 may contribute to tumor growth by amplifying proliferative signaling or inhibiting apoptosis." (PMID 41266441, 2025). "These T cell subsets are essential for immune surveillance and the maintenance of anti-tumor immunity, which reflects that STX16 may contribute to the activation and persistence of tumor-specific T cell responses." (PMID 41266441, 2025). "Preliminary studies suggest that STX16 may regulate tumor cell proliferation, migration, and invasion by affecting vesicle trafficking and signal transduction pathways." (PMID 41266441, 2025).
tumor (continued). "However, the precise mechanisms by which STX16 modulates immune cell function and contributes to tumor progression are yet to be elucidated and warrant comprehensive experimental validation." (PMID 41266441, 2025). "The expression of STX16 may directly influence tumor progression, supported by STX16’s role in regulating membrane trafficking, which could facilitate the delivery of growth factor receptors and adhesion molecules to the plasma membrane, thereby enhancing proliferative and invasive capabilities." (PMID 41266441, 2025). "In vivo validation confirmed icaritin suppressed tumor growth and M2 macrophage infiltration via the ALDOB/STX16/autophagy/STAT3 axis." (PMID 41731604, 2026). "Immune populations may exert a protective anti-tumor effect, counteracting the negative impact of high STX16 levels." (PMID 41266441, 2025). "The consistency of STX16’s prognostic impact across histologic grades and TNM stages emphasizes its central role in tumor evolution, regardless of differentiation status." (PMID 41266441, 2025).
infection (1 paper, 2023). The state of being infected such as from the introduction of a foreign agent such as serum, vaccine, antigenic substance or organism. "In conclusion, the role of STX16 in SARS-CoV-2 biology could be more relevant for the virus uptake than for the secretion of newly generated virions, which is underlined by the very slow infection rate in STX16-depleted cells." (PMID 37632105, 2023). "Interestingly, the strongest decrease in infection was detected for the knockouts of three vesicular trafficking proteins (VTI1A, STX12 and STX16), highlighting the important role of vesicular trafficking for SARS-CoV-2 infection and replication." (PMID 37632105, 2023).
STX16 also shares sentences with these, for which no sentence is quoted: esophageal squamous cell carcinoma (2 papers); hepatocellular carcinoma (2); acrodysostosis (1); acute lymphoblastic leukemia (1); Alzheimer disease (1); amyotrophic lateral sclerosis (1); depression (1); gastrointestinal stromal tumor (1); genetic diseases (1); head and neck cancer (1); lung adenocarcinoma (1); metabolic disease (1); Sepsis (1).